TNF (tumor necrosis factor)
Diseases named in the same sentence as TNF in open-access papers (continued):
Sharing a sentence is not in itself a finding about the gene and the disease.
colitis (continued). "In dextran sulphate sodium-induced colitis mice, magnolol ameliorated disease activities index and suppressed expression levels of IL-1β, IL-12, and TNF-α via the regulation of NF-κB and peroxisome proliferator-activated receptor-γ pathways." (PMID 38541664, 2024). "On the other hand, DHA administration significantly decreased TNF-α levels compared to the colitis group (p < 0.05)." (PMID 39105785, 2024). "Tacrolimus works by suppressing the release of the cytokines IL-2, TNF-α, and interferon γ, thereby inhibiting T cell activation and ultimately controlling colitis symptoms." (PMID 39311981, 2024). "IL-6 and TNF-α levels were significantly increased in the colitis group compared to the control group (p < 0.01 and p < 0.05, respectively)." (PMID 39105785, 2024). "Psychological stress activates the sympathetic nerves and decreases the vagal tone, inhibits its anti-inflammatory effects, promotes TNF-α production by macrophages, and exacerbates colitis progression." (PMID 39355776, 2024). "These cytokines play critical roles in the pathogenesis of colitis, with IL-6, TNF-α, and IL-1β promoting immune cell recruitment and tissue damage, while MCP-1 contributes to macrophage activation and mucosal injury." (PMID 39682761, 2024). "The SeNPs showed anti-colitis actions in various groups by decreasing the effect of IL-1 and TNF-α in a concentration-dependent manner." (PMID 38796570, 2024). "The cytokines TNF-α and IL-17 play an important role in its pathogenesis, while histologically induced colitis is characterized by mucosal infiltration with neutrophils and macrophages." (PMID 39597805, 2024). "A key feature of AA-induced colitis is immune cell infiltration, producing high levels of proinflammatory cytokines such as TNF-α and IL-1β." (PMID 39199130, 2024). "Compared to the levels in the normal group, the proinflammatory cytokines (e.g., IFN-γ, TNF-α, IL-17A, IL-1β and IL-6) were significantly elevated in the colitis group, suggesting that mice bearing colitis have an increase in proinflammatory cytokines." (PMID 38396052, 2024). "In both acute (4%) and chronic (2%) DSS colitis mouse models, mice administered walnut phenolic extract once daily via oral gavage (20 mg/kg) had attenuated TNF-α-induced IκB phosphorylation/degradation and NF-κB DNA binding activity." (PMID 39203780, 2024). "An increasing body of studies has demonstrated that a notable elevation in proinflammatory cytokines, such as IL-6, TNF-α, and IL-1β, constitutes the primary characteristic of colonic injury during the course of colitis development." (PMID 39594091, 2024). "SASP can reduce oxidative stress and the inflammatory response in TNBS-induced colitis model rats by reducing the expression of TNF-α and IL-1β and inhibiting IL-6/JAK2/STAT3 signal transduction." (PMID 39318778, 2024). "For example, the active extract of ginseng (a plant used in traditional Chinese medicine) has been shown to reduce colitis symptoms by decreasing the levels of IL-1β and TNFα and promoting M2 macrophage polarization." (PMID 38892549, 2024). "An earlier experiment demonstrated that L. rhamnosus GG Effector Protein HM0539 substantially mitigated inflammation and downregulated IL-6, IL-1β, and TNF-α in murine colitis." (PMID 37639209, 2024). "By modulating immune responses and inhibiting pro-inflammatory cytokines, EGCG has demonstrated significant potential in alleviating symptoms of colitis and other TNF-α-mediated diseases." (PMID 39597805, 2024). "In studies of colitis, it has been found that the abundance of Alistipes is negatively correlated with TNF-α and IL-1β levels." (PMID 39410114, 2024). "Using a dextran sulphate sodium (DSS)‐induced mouse colitis model, we observed that BsNb‐Fc exhibited greater potency than anti‐TNF‐α mAb IFX and effectively alleviated intestinal mucosal inflammation." (PMID 38533646, 2024).
colitis (continued). "FICZ provides protection against colitis by reducing the production of pro-inflammatory cytokines such as IL-17, IL-1β, IL-6, TNF-α, and IFN-γ, while promoting anti-inflammatory IL-22 production from Th17 cells." (PMID 39767818, 2024). "Taken together, our results indicate that macrophages in the colonic LP facilitate the development of colitis via the production of inflammatory cytokines, such as TNFα and p40, in the T cell-transfer colitis model." (PMID 38012544, 2023). "SCFA has also been reported to ameliorate colitis through suppressing proinflammatory cytokines, such as TNF-α and IL-6." (PMID 36902109, 2023). "Consistent with the observations in human UC, we found that the reduction of Gab1 expression in colonic tissues was significantly rescued after anti-TNF treatment in the DSS-induced colitis model." (PMID 36795486, 2023). "RvE1 suppresses pro-inflammatory cytokine TNF-α production, reducing leukocyte-mediated tissue damage and gene expression, ultimately improving histological scores in colitis mice and preventing colitis onset." (PMID 37868958, 2023). "Previous reports have identified inflammatory cytokines such as IL-17, TNF-α, IL-23, and IL-6 as key players in the development of colitis." (PMID 37836692, 2023). "The representative secreted cytokines are IL-1β, IL-6, and TNF-α, and these induce systemic pro-inflammatory responses, including colitis." (PMID 37569708, 2023). "Regulated the colitis gut microbiota, protected the mucosal barrier system, improved the antioxidant levels, decreased the weight loss and DAI, reduced the expression of TNF-α, up-regulated the expressions of IL-10." (PMID 37485519, 2023). "Oral live ADS024 treatment reduced weight loss, disease activity, colonic mucosal injury, and colonic expression of interleukin 6 (IL-6) and TNFα in dextran sodium sulfate (DSS)-treated mice with colitis." (PMID 38268707, 2023). "DPA attenuates inflammation in DSS-induced colitis model; modulates pro-inflammatory cytokines (TNF-α, IL-1β, IL-6) and anti-inflammatory cytokine (IL-10); inhibits synthesis of pro-inflammatory eicosanoids (PGE2, LTB4)." (PMID 37868958, 2023). "In accordance with the preceding investigations, this study revealed increased levels of TNF-α immunostaining after AA-colitis induction and augmented levels of IL-6." (PMID 37895902, 2023). "Quercetin, a flavonoid with antioxidant properties, can potentially reduce TNF-α levels and increase IL-10 levels in C. rodentium-induced experimental colitis models." (PMID 37465689, 2023). "Both RvD1 and RvD5 diminish leukocyte adhesion, migration, and endothelial adhesion activated by TNF-α, which exhibit protective effects against colitis." (PMID 37868958, 2023). "Previous research has revealed that heat-killed L. sakei K040706, which preserve their cell wall components, protect against DSS-induced colitis by suppressing inflammatory mediators such as nitric oxide, TNF-α, IL-1β, and IL-6." (PMID 37317332, 2023). "Ameliorated colitis symptoms, improved the intestinal barrier integrity, decreased the levels of IL-6, TNF-α." (PMID 37485519, 2023). "L. fermentum reduced the signs of colitis and pro-inflammatory cytokines such as TNF-α, IL-6, IFN-γ and IL-12." (PMID 36986118, 2023). "The levels of IL-1β, TNF-α and IL-6 in the colitis tissues of β6-KO mice were lower than those of WT mice." (PMID 37223685, 2023). "M1 macrophages are the main cellular sources of inflammatory cytokines, such as TNFα and p40, which are indispensable for the development of colitis." (PMID 38012544, 2023). "It was also reported that the levels of TNF-α and IL-6 were altered in the serum of mice with early-stage colitis induced by one week of DSS administration." (PMID 36900589, 2023). "In the present study, PHI efficaciously suppressed the expressions of TNF-α, IL-1β, and IL-6 in colitis mice." (PMID 36768559, 2023).
colitis (continued). "Using a combination of flow cytometry and single‐cell transcriptome analyses, we identified tumor necrosis factor (TNF)‐expressing monocytes as key mediators of stress‐induced colitis exacerbation." (PMID 37885336, 2023). "In our previous study, the prototype ITA aggravated DSS-induced colitis and increased the levels of pro-inflammatory cytokines TNF-α, IL-1β, and IL-6 secreted by macrophages in vitro." (PMID 36770726, 2023). "UC is a repeated colon inflammation characterized by the infiltration of inflammatory cells and expression of NF-kB-dependent pro-inflammatory biomarkers like TNF-α and IL-6." (PMID 37895902, 2023). "The mechanism of expression and inhibition of IL-1β and TNF-α production in intestinal macrophages improved colitis symptoms." (PMID 37371649, 2023). "On the other hand, an experimental study that induced acute colitis with 2.5% DSS for 5 days observed increased TNF-α levels and maintenance of IL-10 levels of the livers of these animals." (PMID 37577725, 2023). "QA at 60 (p < .05, F.C: −4.1) and 100 (p < .01, F.C: −25.64) mg/kg also attenuated the TNF‐α gene expression in comparison to the colitis values." (PMID 37647443, 2023). "Clinically, TNFα blockade can be used to treat checkpoint-induced colitis concurrently with maintained dosing of the immunotherapy." (PMID 37461742, 2023). "Our results suggest that the use of AO treatment, especially the optimal concentration of ATR, confers therapeutic advantages in the context of colitis by prohibiting the expression of proinflammatory cytokines such as IL-6 and TNF-α." (PMID 37959758, 2023). "TNF plays diverse proinflammatory roles in colitis by binding to the TNFR1 and TNFR2 receptors and activating the PI3K–AKT pathway within cells." (PMID 37959758, 2023). "Surprisingly, in colitis, quercetin promotes M2 macrophage polarization to decrease the secretion of proinflammatory cytokines such as TNF-α, IL-23, and IL-12 in colonic tissue." (PMID 37107341, 2023). "In a separate Apcmin/Il-10−/− mouse model, tumor necrosis factor-alpha (TNF-α) neutralizing antibodies attenuated colibactin-producing E. coli-induced colitis and CRC development, highlighting the significance of inflammatory signaling in tumorigenesis." (PMID 37884500, 2023). "The colitis-induced rats had substantial improved healing of their colitis that was evidenced by lower colonic expressions of TNF-α, IL-1β, and hypoxia-inducible factor 1-α." (PMID 36814502, 2023). "Turmeric-derived exosome-like nanoparticles suppressed the expression of pro-inflammatory cytokines, such as TNF-α, IL-6, and IL-1β, promoted the levels of antioxidant genes, particularly HO-1 by inactivating NF-κB pathway, and alleviated colitis." (PMID 37653406, 2023). "Murine colitis-derived intestinal organoids stimulated by LPS show reduced mRNA expression of inflammatory mediators such as TNF-α and lipocalin-2 (LCN2) when treated with quercetin." (PMID 37701897, 2023). "The pro-inflammatory cytokines such as IL-1β and TNF-α were involved in the inflammatory process in DSS-induced colitis." (PMID 35838945, 2023). "We verified this theory by ELISA and found that IL-1β, IL-6, and TNF-α in the colon tissue of DSS-induced colitis mice were significantly increased, showing a strong anti-inflammatory process." (PMID 36832972, 2023). "The increase in TNF- α production in colon and hepatic tissues of the colitis rat control group was significantly reduced by oral gavage with the probiotic L. paracasei strain MSMC39-1." (PMID 36986118, 2023). "In the context of intestinal inflammation, TNF-α has a crucial role in colitis pathogenesis as it induces ROS production and provokes epithelial cell apoptosis." (PMID 37111290, 2023). "It was confirmed that TNF-α played a vital role in regulating intestinal epithelial cell apoptosis and survival in the colitis model." (PMID 37762155, 2023).
colitis (continued). "On the contrary, HIF-2 exacerbates colitis by inducing the release of tumor necrosis factor-alpha (TNFα) in epithelial cells." (PMID 36634466, 2023). "In our cohort, From the 19 patients in remission at week 52, 57.9% were females, 78.9% had extensive colitis, 68.3% had previous anti-TNF, and 52.6% previously used vedolizumab." (PMID 36777366, 2023). "To characterize the anti-inflammatory therapeutic potential of PR1P in TNBS-induced colitis, we quantified plasma levels of the pro-inflammatory mediators IL-1β, IL-6 and TNF-α on Day 7 following necropsy." (PMID 37187742, 2023). "PFKFB3 increased IL-1β and TNF-α in intestinal epithelial cells to promote colitis-related colorectal cancer tumorigenesis." (PMID 38098990, 2023). "The TNF-loaded hybrid system significantly improved IBD compared with the i.v. of TNF in a colitis mouse model." (PMID 38260737, 2023). "Bhat and co-workers have reported that claudin-1 upregulation in colitis is mediated by tumor necrosis factor (TNF)-α." (PMID 37627123, 2023). "In DSS-induced colitis mouse models, the specific deletion of GPR35 in macrophages resulted in elevated inflammation associated with a decrease in TNF production in macrophages." (PMID 38035084, 2023). "The serum concentration of TNF-α in colitis mice was elevated, potentially mediated by the upregulation of TNF-α gene expression in colon tissue." (PMID 37761037, 2023). "The closely correlated pro-inflammatory cytokines in lipid metabolism are TNF-a, IL-17a, IL-4, and IL-6, and these molecules promote colitis progression." (PMID 37569708, 2023). "The acute inflammatory response in DSS-induced colitis is represented by increased expression of IL-1β, IL-6, and TNF-α in the colon." (PMID 36768278, 2023). "In the colon single-cell culture condition, the levels of Th1 cells producing IFN-γ and TNF-α in DSS-colitis were considerably increased by FimH administration." (PMID 38077339, 2023). "In particular, EP-1 has shown the ability to increase the activity of superoxide dismutase enzymes in an in vivo experimental colitis model, thereby reducing malondialdehyde and proinflammatory markers (i.e., TNF-α, IL-1, and IL-6)." (PMID 37465689, 2023). "We previously showed that GPR4 antagonists in the DSS-induced colitis mouse model reduced TNF-α mRNA levels in intestinal tissues when compared with a vehicle control." (PMID 37894341, 2023). "Next, we analyzed the ability of M1 macrophages to secrete TNFα and p40, which are detected in colonic tissues during colitis development." (PMID 38012544, 2023). "It did not affect the transcription of TNF, IL-6, and IL-10, suggesting that additional proinflammatory cues, as provided during DSS colitis, are required to induce TNF upregulation." (PMID 36413219, 2023). "It was shown that rectal administration of siRNA targeting TNF-a resulted in relative mucosal resistance to experimental colitis using a mouse model of inflammatory bowel disease." (PMID 37169818, 2023). "In mice, TDNPs were found to alleviate colitis symptoms by regulating the expression of pro-inflammatory cytokines (TNF-α, IL-6 and IL-1β) and the antioxidant gene HO-1, while also deactivating the NF-κB pathway." (PMID 37371649, 2023). "Using experimental colitis mice, Bifico was found to ameliorate gut inflammation by decreasing the tumor necrosis factor-α (TNF-α) level." (PMID 35918555, 2023). "The increased release of pro-inflammatory mediators, like TNF-α, can trigger apoptosis, which has an important role in animal colitis models." (PMID 37895902, 2023). "Experimental evidence showed that SYK inhibitor significantly alleviated DSS-induced and TNBS-induced colitis by regulating TGFβ, TNFα, and IL-1β, which are also important in the course of PSC." (PMID 37229242, 2023). "The main GBE component flavonoids, such as kaempferol and isorhamnetin, have been shown to reduce IL-1β, IL-6, and TNF-α within DSS-induced colitis animal models." (PMID 37111225, 2023).
colitis (continued). "At present, some drugs are used to suppress colitis-related inflammation and the immune response to alleviate symptoms, such as tumor necrosis factor (TNF-α) therapy, corticosteroids, aminosalicylates, and antibiotics." (PMID 37762155, 2023). "Mice treated with SCH experienced significant weight gain, effectively alleviating the severity of colitis, and decreasing the levels of inflammatory factors such as TNF-α, IL-1β, IL-18, IL-6, and other related proteins (NLRP3, Caspase-1, SGK1) in UC mice." (PMID 37674245, 2023). "Valeric acid can inhibit the growth of Clostridium difficile and thereby regulate intestinal homeostasis, whereas sodium butyrate can reduce IL-6 and TNF-α levels and thereby improve colitis in mice." (PMID 37065247, 2023). "A reduction in CCL2 and TNF‐α production was observed after oral administration of a butyrate derivative in mice with colitis." (PMID 36459573, 2023). "Supplementation with B. vulgatus attenuated symptoms of colitis in mice and decreased the expression of TNF-α, IL-1β, and IL-6 in the colon." (PMID 36902001, 2023). "High levels of TNF signalling specifically in myeloid cells in CPI-colitis patients have also been reported." (PMID 36776862, 2023). "Milk extracellular vesicles (mEVs) alleviate DSS-induced colitis by reducing TNF-α and IL-6 expression." (PMID 37389342, 2023). "In a model of experimental colitis, oral administration of butyrate has been shown to decrease TNF‐α, to block NF‐κB signalling and to reverse histone acetylation." (PMID 36459573, 2023). "After 10 days, we found that Gpr120−/− mice demonstrated more severe colitis compared to WT mice, as demonstrated by higher pathological scores and elevated intestinal TNF-α expression." (PMID 36927391, 2023). "Increased NF-κB expression in mucosal macrophages is accompanied by increased expression of TNF-α and chemokines in TNBS- or IL-10-deficient-induced colitis mice." (PMID 36926182, 2023). "It is proved that oral TDNPs can reduce proinflammatory cytokines (TNF-α, IL-6 and IL-1β), upregulate antioxidant gene HO-1 to relieve colitis in mice and accelerate colitis regression." (PMID 37033644, 2023). "IL-22 mRNA was encapsulated in a novel nanoparticle and fed to a mouse model of acute colitis, and recovery of colonic length and tissue damage was observed, with concomitant reductions in TNF-α, IL-6 and IL-1β expression." (PMID 37389342, 2023). "TNF-α is one of the cytokines considered markers in the DSS colitis model, and its gene expression and protein concentrations appear to increase in the acute phase." (PMID 36792680, 2023). "Currently, anti-TNF agents (e.g., infliximab) are recommended for the treatment of immunotherapy-related serious adverse events (e.g., colitis and hepatitis)." (PMID 37958479, 2023). "Dextran sodium sulfate (DSS)-induced colitis was used as the in vivo model, and tumor necrosis factor-α (TNFα)-stimulated HT-29 cells as the in vitro model." (PMID 37047133, 2023). "Terpenoid component bilobalide can inhibit the expression of IL-1β, IL-6, and TNF-α in DSS-mediated colitis." (PMID 37111225, 2023). "In IBD, goblet cell numbers have been reported to decrease, while anti-TNF treatment has been shown to lead to an increase in goblet cell numbers in mouse colitis." (PMID 37643009, 2023). "In previous studies, ursolic acid has been proved to relive DSS-induced colitis in mice by reducing the content of malondialdehyde, IL-1β and TNF-α and increasing superoxide dismutase activity in mice colon tissues." (PMID 37161415, 2023). "The expression of proinflammatory genes, such as IL‐6, TNF‐α and IL‐1β was significantly lower in the colon of KO mice than in WT mice in both acute colitis and tumour samples." (PMID 37341064, 2023). "A previous study in mice has shown that blocking IL-17 leads to worsening of colitis by increasing tumor necrosis factor-α, interferon-γ, IL-6, and cytokines that promote the inflammatory response." (PMID 37033665, 2023).